RAC1 (Rac family small GTPase 1)
Diseases named in the same sentence as RAC1 in open-access papers (continued):
Sharing a sentence is not in itself a finding about the gene and the disease.
glioblastoma (continued). "Thus, we have shown that Rac1 regulates glioblastoma cell invasion and proliferation." (PMID 22966858, 2012). "Most importantly, the function of SOXC factors can be replaced by chemicals targeting RhoA, RAC1, CDC42, or their effectors, indicating a critical role of Rho GTPases played during neuronal reprogramming of human glioblastoma cells." (PMID 39390804, 2024). "With glioblastoma tissue that has an overexpression of both NF2 and Ezrin, Ezrin can inhibit Rac1 inhibition, leading to proliferation." (PMID 39796693, 2024). "A study revealed that NKCC1/SLC12A2 was highly expressed in Glioblastomas and it promoted EMT-like process via RhoA and Rac1 signaling pathways." (PMID 38396064, 2024). "GSK-3beta has been shown to interact with focal adhesion kinase (FAK), Ras-related C3 botulinum toxin substrate 1 (Rac1) and c-Jun-N-terminal kinase (JNK) in glioblastoma." (PMID 27999207, 2017). "DOCK7 is a RAC-GEF with the potential to regulate F-actin organization, consistent with previous publications reporting DOCK7-mediated RAC1/CDC42 - PAK1 activation in the DNA replication stress response 122, and the promotion of glioblastoma cell invasion by DOCK7 via RAC activation." (PMID 37064875, 2023). "Rac1 and Rac3 have previously been reported to have opposite effects on neuronal cell adhesion, and only Rac1 and not Rac3 depletion reduced lamellipodia in glioblastoma cells." (PMID 29510700, 2018). "From these results, we conclude that the influence of Rac2 and Rac3 on the formation and proliferation of glioblastoma-stem like cells is no less than Rac1." (PMID 28160553, 2017). "Previous data from our laboratory have demonstrated that Rac1 is critical for glioblastoma cell proliferation in the absence, but not in the presence of serum." (PMID 22966858, 2012). "Our study also revealed that down-modulation of hMena expression induces activation of Rac1 in glioblastoma cell lines, but not in epithelial HeLaS3 cells." (PMID 19277120, 2009). "Another Rac GEF that promotes Rac1-mediated invasion in glioblastoma cells is PREX1, which is overexpressed in GBM and responds to the presence of the upregulated Pi3K pathway." (PMID 32089990, 2020). "Thus, local Ca2+ signals elicited by these ion channels might promote Ca2+/CaM binding to CaMK II, leading to Akt-mediated Rac1 activation through Tiam1, suggesting participation of TRPV4-mediated Rac1 regulation in glioblastoma progression." (PMID 33240883, 2020). "DOCKs are activated by oncogenic RTKs, where in glioblastoma, the oncogenic epidermal growth factor receptor (EGFRvIII) and platelet derived growth factor receptor (PDGFR) induced Src-mediated tyrosine phosphorylation of DOCK1 to activate Rac1 and promote cell migration and invasion." (PMID 32322580, 2020). "Since Rac1 is also important for glioblastoma multiforme (GBM) cell migration and invasion, it has been suggested to use NDV for targeted therapy against GBM." (PMID 31480379, 2019). "Like vacuoles formed during SV40 infection, HRas-induced vacuole formation in glioblastoma cells was independent of ERK signaling and blocked by chemical inhibition of Rac1." (PMID 33028008, 2020). "Together, these observations indicate a crucial role of the Graf (ARHGAP26)/Rac1/Cdc42 axis, not DOCK180 or ELMO1, in CD151-α3 integrin complex-mediated signaling in glioblastoma." (PMID 26377974, 2015). "Our finding that RhoG contributes to Rac1 activation downstream of EGFR in glioblastoma cells however, contrasts to published observations that EGF-stimulated Rac1 activation is independent of RhoG in HeLa cells." (PMID 22966858, 2012).
colon carcinoma (63 papers, 2004 to 2025). "To evaluate the effect of RAC1A159V mutation on tumor cells, we used CRISPR-Cas9–mediated knock-in technology to introduce the A159V mutation to the endogenous RAC1 locus of the MC38 colon cancer cells." (PMID 41160695, 2025). "We have previously shown that, in normal colon mucosa about 95% of the pre-mRNA transcribed from the RAC1 gene yields the RAC1 mRNA, but in colon tumours, the alternative transcript encoding RAC1B can increase to up to 20% of the total RAC1 gene-derived mRNA." (PMID 35326545, 2022). "The incidence of KRAS activation in CRC led us to evaluate with Dr P. Jordan (Lisbon, Portugal) the status of other small GTPases and to identify a novel splice variant of Rac1 overexpressed in human colonic tumors that we designed Rac1b." (PMID 32178475, 2020). "We investigated the effects of AZA197 treatment on RhoA, Rac1 and Cdc42 activities and associated molecular mechanisms in colon cancer cells in vitro." (PMID 24279335, 2013). "Rac1 overexpression has been detected in many tumor types, including breast, lung, and colon cancer; and Rac1b, a fast-cycling splice variant of Rac1, has been observed to be highly expressed in some breast and colon cancers." (PMID 22494620, 2012). "Our data indicate that a strong decrease in Cdc42 and Rac1 activity is clearly associated with increased colon cancer invasiveness." (PMID 23144867, 2012). "More advanced colon cancer samples often contained K-Ras mutation, which elevated two signaling branches: K-Ras/RAC1/JNK2 cascade and K-Ras/RAC1/PAK1 cascade." (PMID 35359365, 2022). "On the other hand, in the human colon cancer cells we tested, the endogenous activity of Cdc42 appeared to be much lower than that of Rac1 under physiological conditions." (PMID 35110666, 2022). "RAC1 protein expression in liver metastatic tissue was higher than in colon tumor itself, and the higher the expression of RAC1, the shorter the survival time." (PMID 33406731, 2021). "Isoalvaxanthone, a natural xanthone derivative isolated from plants, also had similar activities in SW620 colon cancer cells, additionally inhibiting Rac1 factor and subsequently reducing the expression and activity of MMP-2 and MMP-9." (PMID 34680113, 2021). "Overexpression of RAC1 in colon cancer cells induced an aberrant expression of EMT markers (vimentin, N-cadherin, E-cadherin) and promoted invasion, migration and metastasis in vitro and in vivo." (PMID 33406731, 2021). "The cellular inhibitor of apoptosis protein 2 (cIAP2/BIRC3) also upregulates and activates Rac1, and promotes cell migration and wound healing of human colon cancer Caco-2 cells in vitro." (PMID 32178475, 2020). "As illustrated by RAC1 in colon cancer, RAC1 generates three splicing isoforms, and the fourth exon is skipped in normal tissues and included in tumor tissues." (PMID 29843604, 2018). "In this study, we compared Rac1 expression in in situ colon cancer tissue to hepatic metastatic tumor tissue." (PMID 27791203, 2016). "Knockout of the rat Rac1 gene exon-3b or knockdown of endogenous Rac1b in HT29 human colon cancer cells downregulated only the AKT2/MCL1 pathway." (PMID 26918455, 2016). "Mounting evidence showed that Rac1 expression and activity are both increased in many cancer types, including colon cancer and it enhanced the metastasis in cells." (PMID 27791203, 2016).
colon carcinoma (continued). "Knockout of the rat Rac1 gene exon-3b or knockdown of endogenous Rac1b in human colon cancer HT29 cells downregulated only the AKT2/MCL1 pathway." (PMID 26918455, 2016). "Base on these findings, we created dtACPP-PEG-DGL (dtACPPD)/shRac1 nanoparticles and demonstrated that they downregulated Rac1 expression in colon cancer cells." (PMID 27791203, 2016). "In other cellular processes, such as osteoblastogenesis, or in colon cancer cells, a Rac1/JNK2-dependent phosphorylation of β-catenin was described at sites that regulate its nuclear accumulation and signalling function." (PMID 25426554, 2015). "TCF/β-catenin strongly activates c-jun transcription in colon cancer cells suggesting that Rac1 has the ability to up-regulate c-myc transcription via multiple Wnt pathways and contribute to tumorigenesis." (PMID 26403202, 2015). "Babykutty reported that the activity and expression of Rac1 are promoted by NO in a time-dependent manner in colon cancer cells." (PMID 25799230, 2015). "Selective blockade of Rac1 activity suppressed the invasion and migration of HCT116 and LoVo cells, implying the involvement of Rac1 in the radixin-mediated invasion and migration of colon cancer cells." (PMID 25136657, 2014). "In summary, our present work demonstrates that radixin can promote the invasion of colon cancer cells by activating Rac1-ERK pathway and upregulating MMP-7 production." (PMID 25136657, 2014). "The results presented herein suggest decreasing DGKζ expression or function is a potential route to reducing Rac1 and RhoA activity and the migratory ability of colon cancer cells." (PMID 24646293, 2014). "Studies have reported that Rac1 can regulate multiple intracellular signaling pathways in colon cancer, such as PI3K/AKT and MAPK pathways." (PMID 25136657, 2014). "Localised disruption of E-cadherin-mediated cell–cell adhesion sites was recently observed in invasive human colon carcinoma cells and this disruption was associated with relocalisation of IQGAP1, a Rac1/Cdc42 effector molecule." (PMID 14735193, 2004). "Similarly, RAC1b—a constitutively activated isoform of RAC1—was found to be upregulated in colon cancer tissues, and emerged as a potential target to overcome chemotherapy resistance in colon cancer." (PMID 33406731, 2021). "Furthermore, Rac1 protein levels were higher in colon cancer liver metastases compared with primary colon tumor, and patients with high Rac1-expressing CRC showed shorter overall survival." (PMID 32178475, 2020). "Our previous study found that RAC1 could significantly induce the EMT of colon cancer cells, which may be related to the positive regulation of Rac1/PAK1/LIMK1/Cofilins signaling pathway." (PMID 32411607, 2020). "Interestingly, ARHGAP11A expression induced an increase in the relative Rac1 activity by blocking RhoA signaling, which led to an increase in the invasion ability of colon cancer cells." (PMID 33126743, 2020). "Moreover, a reduction in protein expression levels of phospho-Rac1/Cdc42/Rac1/Cdc42 ratio, Cofilin, Vimentin, and phospho-Paxillin was found in both colon cancer cell lines studied." (PMID 32143529, 2020). "Collectively, we develop a multifunctional nanoparticle formulation of afatinib and miR-139 with targeting, penetrating, and pH-responsive characteristics for simultaneous modulation of EGFR/HER/Ras/Akt/Rac1/STAT3/MAPK/EMT/Bcl-2 pathways to increase the sensitivity of colon cancer cells to afatinib." (PMID 31426807, 2019). "In this study, we observed that expression of Rac1, a key molecule for cytoskeletal reorganization, was higher in hepatic metastatic tumor tissue compared with prime colon cancer tissue and that patients with high Rac1-expressing colon cancer showed shorter survival time." (PMID 27791203, 2016). "In this study, we found that Rac1 was related to the metastasis and survival time of colon cancer." (PMID 27791203, 2016).
colon carcinoma (continued). "Rac1 expression and activity are both enhanced in colon cancer and could speed up the metastasis of cancer cells." (PMID 27791203, 2016). "This study demonstrated up-regulated active Rac1, CDC42 and RhoA expression in Hes1-expressing colon cancer cells, whereas down-regulated active Rac1, CDC42 and RhoA expression in Hes1-silencing cells, which indicated that Hes1 induced cytoskeleton reconstruction of colon cancer cells." (PMID 26452029, 2015). "Finally, we identified that radixin promoted invasion and migration of colon cancer cells by activating Rac1-ERK pathway and by increasing MMP-7 production." (PMID 25136657, 2014). "Consistently, we found that radixin was necessary for the activation of Rac1 in colon cancer cells." (PMID 25136657, 2014). "We first examined Rac1 activation in SW620 colon cancer cell lysates." (PMID 24279335, 2013). "Alternatively, Rac1 may exert its stimulatory effects on β-catenin/TCF-mediated transcription in colon cancer cells though the downstream effector protein Pak1." (PMID 18826597, 2008). "GYS32661 is currently developed as an anticancer agent, essentially positioned to treat breast and colon cancers, but this potent Rac1 inhibitor could be envisioned for the treatment of other malignancies associated with an overactivation of Rac1, such as bladder cancers." (PMID 35740379, 2022). "Moreover, the lack of Rac1 impeded tumor formation as well as prohibit Kras-mutant tumor development, suggesting that RAC1 could be a potential curative target for initial colon cancer stage." (PMID 33406731, 2021). "Much evidence support the importance of Rac1 in colorectal adenocarcinoma and it has been shown that overexpression of Rac1 in colon cancer cells accelerates the tumorigenic process which may be suppressed by inhibition of Rac1 expression with RNA interference." (PMID 24279335, 2013). "Given that the activity of Rho GTPases is crucial for cancer cell proliferation and motility, and NEK2 enhanced the activity of RhoA and Rac1, we investigated the impact of NEK2 on the proliferation and metastatic behavior of colon cancer cells." (PMID 39768163, 2024). "Rac1 and CTTN play major roles in promoting epithelial tumor metastasis, and the activation of these two genes has been reported in ovarian, breast, and colon cancers." (PMID 37970440, 2023). "Mechanistically, CTTN increases accumulation of DOCK1 and Rac1, and DOCK1 silencing partially abolishes the migration and invasion capacity induced by CTTN in SW480 colon cancer cells." (PMID 32178475, 2020). "In colon cancer cells, increased CAV1 expression enhanced migration and invasion in vitro via pathways requiring Src-family kinases, as well as Rac-1 activity." (PMID 29340103, 2017). "Since radixin can induce Rac1 and ERK1/2 activation these results suggest that radixin influences MMP-7 production via Rac1 and ERK1/2 activation in colon cancer cells." (PMID 25136657, 2014). "Further findings showed that radixin induced the activation of Rac1-ERK pathway, leading to an increase in MMP-7 production, thereby contributing to the invasion and migration of colon cancer cells." (PMID 25136657, 2014). "Since radixin can regulate the activation of Rac1 and ERK1/2 and Rac1-ERK signaling is essential for the colon cancer cell invasion and migration, it is possible that radixin promotes the invasion and migration through activation of Rac1-ERK pathway." (PMID 25136657, 2014). "The exact molecular signaling pathways mediating this effect are yet to be discovered, however, we have previously found that leptin promotes colon cancer cell metastatic potential by affecting PI3K and Src kinase pathways and activating Rac1 and Cdc42." (PMID 24073224, 2013). "In colon cancer cells, rictor gene-silencing induces mesenchymal-epithelial transition (MET) and inhibits cell motility by effects on both RhoA and Rac1." (PMID 24312263, 2013).
colon carcinoma (continued). "Their inhibition has been proposed as a strategy to mitigate invasion and migration of colon cancer cells, being involved in the regulation of EMT and cytoskeleton rearrangement, via RhoA and Rac1 signaling, which are members of the GTPases family that regulates actin filament assembly." (PMID 35645325, 2022). "The link between EMT and Rac1 has been studied more deeply in other types of cancers, notably in lung and colon cancers." (PMID 35740379, 2022). "Furthermore, we conclude that Rac1 is fundamental for NSC growth in vitro and its inhibition results in arrest of the cell cycle, as noted for colon cancer cells, and/or cell death by apoptosis." (PMID 34041508, 2021). "VB significantly inhibits tumor cell metastasis and invasion by inhibiting Rac-1, hypoxia inducible factor-1α (HIF-1α), and Zeb-1 signaling pathways, which may be the most metastatic phenotype of colon cancer-suitable drug candidates." (PMID 33768139, 2021). "In agreement with our data, a previous report demonstrated that a dominant-negative Rac1 mutant drastically inhibits Wnt signaling in colon cancer followed by a decrease in its target gene transcription." (PMID 32983019, 2020). "It is worth noting that, although Tiam1 effects on cellular migration are mediated by Rac1, Tiam1-induced resistance of colon cancer cells to anoikis is independent of the GTPase." (PMID 32178475, 2020). "However, β-catenin and RAC1 were observed to interact with the TCF7 or LEF1 promoter region in both breast and colon cancer cells." (PMID 30650643, 2019). "Based on these results, we suggest that NUMB transcription might be differentially regulated through different binding capacities of other factors, along with RAC1, to the NUMB promoter region in breast or colon cancer cells." (PMID 30650643, 2019). "Similarly, over expression of RhoA, Rac1, and Cdc42 all led to induced COX-2 expression in NIH3T3 cells, MDCK epithelial cells, and HT29 colon cancer cells through a NF-κB dependent mechanism." (PMID 26416248, 2015). "Activation of Rac1-ERK pathway and consequent upregulation of MMP-7 production may contribute to the function of radixin in the regulation of colon cancer cell invasion." (PMID 25136657, 2014). "In colon cancer cells Rac signaling to PAK controls PKC/fascin interactions to regulate their migration, and spingosine1P signaling to PKCε subsequently activates a PLD2-PKCζ-Rac1 cascade to stimulate migration of endothelial cells." (PMID 19400942, 2009). "Overexpression of the Rac1-specific GEF, T-cell lymphoma invasion and metastasis 1 (Tiam1), has been reported in highly invasive breast tumours and colon carcinomas, and may contribute to elevated Rac1 signalling in these cancers." (PMID 18826597, 2008). "An example of ligand-dependent RAGE signaling was in colon cancer cells where AGEs increased cell migration and invasion predominantly through increased activities of iNOS and NF-κB, whereas in the same cells, HMGB1 acted mainly through activation of ERK1/2, Rac1, and Akt." (PMID 33086527, 2020). "Our results support a hypothesis that transgelin interacts with PARP1 and regulates the expression of downstream key genes (CALM1, MYO1F, NCKIPSD, PLK4, RAC1, WAS and WIPF1), which are mainly involved in the Rho signaling pathway in the human RKO colon cancer cells." (PMID 32774160, 2020). "In colon cancer cells, the cytoplasmic and nuclear distribution patterns of RAC1 were maintained, regardless of whether KRT19 was knocked down." (PMID 30650643, 2019). "To test whether the observed decrease in Cdc42 and Rac1 and increase in ROCK activity were both involved in tumour progression to more advanced stages, we treated these three colon cancer cell lines with PDGF to re-activate Cdc42 and Rac1 and/or with Y27632 to block ROCK." (PMID 23144867, 2012). "Nevertheless, in colon cancer cells, despite the similar effect of KRT19 on β-catenin nuclear translocation, nuclear RAC1 levels did not decrease upon KRT19 knockdown." (PMID 30650643, 2019).
colon carcinoma (continued). "In SW620 and HT-29 human colon cancer cells, AZA197 demonstrated selectivity for Cdc42 without inhibition of Rac1 or RhoA GTPases from the same family." (PMID 24279335, 2013). "However, in colon cancer, KRT19 was reported to interact with β-catenin, but not RAC1, and then enhanced the transcription function of LEF/TCF, thus promoting Notch signaling." (PMID 33767587, 2021). "However, in colon cancer, KRT19 was validated to interact with β-catenin but not with RAC1 and then enhance the transcription function of LEF/TCF, thus promoting Notch signaling." (PMID 33767587, 2021).